BRIP1 (BRCA1 interacting DNA helicase 1)
Diseases named in the same sentence as BRIP1 in open-access papers (continued):
Sharing a sentence is not in itself a finding about the gene and the disease.
cancer (continued). "Herein, we conducted a systematic and comprehensive analysis of BRIP1 in pan-cancer." (PMID 37153833, 2023). "The current study noticed statistical significance between DNA methylation and gene expression across multiple cancers, suggesting that DNA methylation could also be one of the factors that regulate BRIP1 expression in cancers." (PMID 36907870, 2023). "Differential analyses showed an increased expression of BRIP1 in 28 cancer types and its aberrant expression could be an indicator for prognosis in most cancers." (PMID 37153833, 2023). "Moreover, Kaplan–Meier curve analysis showed that BRIP1 expression and genetic aberrations were closely related to patient survival in several cancers, indicating their potential for application as new tumor markers and therapeutic targets." (PMID 36932143, 2023). "Besides, the relationship between BRIP1 expression and MSI (microsatellite instability)/TMB (tumor mutational burden)/neoantigen in all TCGA cancers was investigated." (PMID 36907870, 2023). "In addition, a positive correlation was noticed in numerous cancers between the BRIP1-correlated five genes and BRIP1." (PMID 36907870, 2023). "The regulation of RNA modification across cancers could also be responsible for the inconsistent effect of BRIP1 in cancers." (PMID 36907870, 2023). "And it indicated the promising prognostic role of BRIP1 in cancers." (PMID 36932143, 2023). "In the current study, we profiled the features of BRIP1 in 32 TCGA cancer types." (PMID 36932143, 2023). "Furthermore, functional and mechanistic experiments are needed to elucidate the role of BRIP1 in specific cancers." (PMID 37153833, 2023). "Compared to BRCA2, the importance of mutationin BRIP1 does not increase the risk of cancer exposure; however, its product isrecognized as a tumor suppressor and also an oncogene protein." (PMID 39430039, 2023). "At last, we analyzed the prognostic significance of BRIP1 in each cancer." (PMID 36932143, 2023). "The different BRIP1 variation frequency and types across cancers might contribute to their diverse regulation mechanisms in the development and survival of cancers." (PMID 36907870, 2023). "Synthesizing the previous results, we believed that the high expression of BRIP1 could hamper cancer patients' survival and it might be an independent prognostic factor for various tumors." (PMID 37153833, 2023). "The most frequently amplified genes across the pan-cancer atlas were BRIP1 (HDR, 8.04%), POLB (BER, 6.54%), MUS81 (HDR, 6.42%), NBN (HDR, 6.31%), and EXO1 (MMR, 6.26%), while the most frequently deleted genes were BRCA2 (HDR, 6.44%), XRCC2 (HDR, 6.38%), and CUL5 (NER, 6,28%)." (PMID 36081518, 2022). "The identification of BRIP1 and CHEK2 variants in FC HBC or HBOC syndrome families, which have also been reported in BC and OC cases from other populations, supports their role in the risk of these cancers." (PMID 34298626, 2021). "Germline variants in the HR pathway, comprising at least 10 genes, such as BRCA1, BRCA2, ATM, BARD1, BRIP1, CHEK2, NBS1(NBN), PALB2, RAD51C, and RAD51D, lead to inherited susceptibility to specific types of cancers, including those of the breast, ovaries, prostate, and pancreas." (PMID 35008774, 2021). "Other mutated cancer genes included those involved in Wnt signaling (APC, AMER1), mitogen signaling (KRAS, BRAF), epigenetic modification (ARID1A, ARID2, DNMT3A, NCOA3) and DNA repair (RAD50, BRIP1, ERCC5, RECQL4)." (PMID 33776923, 2021). "It has been suggested that BRIP1 may have an anti-oncogenic role, and its downregulation has been observed in multiple types of cancer." (PMID 30800220, 2019). "These may made SNPs of BRIP1 (rs2048718, rs4988344, rs4986764, and rs6504074) be a potential tool for cancer screening and improve early cancer diagnosis." (PMID 29466248, 2018).
cancer (continued). "The BRIP1 mutation c.847T>C and the CHEK2 mutation c.695G>T were found in one of the 504 cancer cases (each) and the ATM mutations c.1595G>A and c.5750G>A were found in two cases (each) of the 710 healthy controls and in six and three cases, respectively, of the 504 cancer cases." (PMID 29659569, 2018). "BRIP1 is a DNA-dependent ATPase and a 5′-to-3′ DNA helicase that achieves its cancer suppression function and DNA double-strand break repair through direct interaction with the highly conserved, C-terminal BRCT (BRCA1 C-Terminal domain) protein domain repeats of the tumor suppressor BRCA1." (PMID 28968953, 2017). "Indeed, mutations within the BRCT repeats on BRCA1 disrupt its interaction with BRIP1 and lead to defects in DNA repair thereby resulting in several forms of cancers." (PMID 28968953, 2017). "For the patients with single primary cancer, among 542 evaluable patients (those with both germline and somatic mutations which were in same or different genes), 25 patients (4.6%) had biallelic events, and the involved genes included ATM, BRCA1, BRCA2, BRIP1, and ERCC5." (PMID 37885353, 2024). "Moreover, the correlation analysis between BRIP1 expression and ten famous cancer-related pathways among 32 cancer types suggested that BRIP1 was highly correlated to the activation of apoptosis, cell cycle, DNA damage response, and inhibition of hormone ER and RNS/MARK signaling pathways." (PMID 36907870, 2023). "Besides, BRIP1 correlations with tumor microenvironment (TME), immune infiltration, immune-related genes, tumor mutation burden (TMB), microsatellite instability (MSI), and immunotherapy as well as antitumor drugs were explored in pan-cancer." (PMID 37153833, 2023). "However, the role of BRIP1 in the carcinogenesis of various cancers remains to be illuminated." (PMID 36907870, 2023). "The genetic landscape and biological function of BRIP1 across pan-cancer remain unclear." (PMID 36907870, 2023). "In our study, a PABC patient carried a VUS in BRIP1 (BRCA1 interacting protein C-terminal helicase 1) which is a gene that contributes to the DNA repair function of BRCA1; the impact of this variant on molecular function and subsequent roles in cancer risk is uncertain." (PMID 34011307, 2021). "In addition, pan-cancer studies provide evidence for factors affecting predisposition to different cancer types, highlighting rare germline cancer susceptibility variants that affect tumour suppressor genes including ATM, BRCA1, BRCA2, BRIP1, and PALB24." (PMID 34253785, 2021). "On the other hand, and to our knowledge, no study has linked BRIP1 to cancer metastasis yet." (PMID 32888398, 2020). "In addition, we identified three heterozygous candidate missense variants in known cancer susceptibility genes (BMPR1A,BRIP1, and SRC), three truncating variants in possibly novel cancer genes (CLSPN,SEC24B, SSH2) and four candidate missense variants in ACACA, NR2C2, INPP4A, and DIDO1." (PMID 30809968, 2019). "The most commonly overexpressed genes in rare cancers included BIRC5 (88%), TOP2A (85%), CDK4 (82%), BRIP1 (76%), MSH6 (66%), and HDAC2 (62%)." (PMID 38347552, 2024). "For the ALT high and TELlow phenotype, the BRIP1 and CLSPN genes were upregulated in 12 different cancer types and the MTND1P23 pseudogene was downregulated in 14 cancer types, and SCGB3A1 in 12 cancer types." (PMID 38763334, 2024). "Mutations in other HR genes, such as PALB2, RAD51C,RBBP8 (also known as CtIP), and BRIP1 (also known as FANCJ/BACH1), are also found in cancers." (PMID 39007266, 2024).
cancer (continued). "When delayed from age 45 years to 50 years, RRSO yielded fewer QALYs and cancers prevented despite slightly larger NMB for RAD51C, RAD51D, and BRIP1 PV carriers." (PMID 38334999, 2024). "Moreover, some other factors may contribute to the diverse prognostic role of BRIP1 in cancers." (PMID 36907870, 2023). "The most altered cancer-related genes include NBN, RAD51C, BRIP1 (mostly with amplification events), and CDH1 (usually with losses or deep deletions)." (PMID 37239898, 2023). "The total BRIP1 CNV frequency was 34.88% (3826 of 10,967 samples) in pan cancer and showed remarkable diversity for individual cancer ranging from 4.4 to 75.38%." (PMID 36932143, 2023). "Correlation between BRIP1 and prognosis, genomic alterations, and copy number variation (CNV) as well as methylation in pan-cancer were further analyzed." (PMID 37153833, 2023). "We have found that the most altered cancer-related genes include NBN, RAD51C, BRIP1 (mostly with amplification events), and CDH1 (usually with losses or deep deletions)." (PMID 37239898, 2023). "Some cancer types with insufficient samples may not represent the BRIP1 mutation profile." (PMID 36932143, 2023). "Other high-penetrant cancer genes BRCA1, APC, STK11 and moderate-penetrant genes BRIP1, CDKN2A, FANCI and MET had a similar frequency 1 (5.8%)." (PMID 37277882, 2023). "In the current work, we found a significantly positive correlation between BRIP1 expression and immune cell infiltration of CAFs and CD8+ T cells in many cancers." (PMID 36907870, 2023). "Of interest, the lowest BRIP1 expression was noticed in subtype C3 in most cancers, except for LGG and KIRC (BRIP1 expression in C5 is the lowest)." (PMID 36907870, 2023). "Among the interface genes in the Her2+_TNBC module, the known cancer-related genes are mostly DNA repair genes, such as BARD1, BRIP1, BRCA1, BRCA2, FANCA, FANCC, FANCD2, and FEN1." (PMID 35992864, 2022). "In this analysis, we only considered genes that were affected in at least four TCGA cases within a cancer type and therefore only seven genes (BRCA1/2, ATM, ATR, PALB2, CHEK2, BRIP1) were included." (PMID 34572800, 2021). "This chromosomal region contains several genes connected to cancers including EME1, BRCA1, ERBB2, NF1, RAD51C, BRIP1, BIRC5 and PPM1D." (PMID 34885154, 2021). "In this analysis, we evaluated the clinical presentation of over 3000 women with PVs in BRIP1, RAD51C, or RAD51D identified by a multigene hereditary cancer panel." (PMID 33926482, 2021). "Several previously known cancer-related genes, including PTPN22, BRIP1, and CEACAM6, were found as hubs in the tumor-related subnetworks." (PMID 30240439, 2018). "Analysis of individual cancer types revealed significant early onset for germline truncations of FANCA in HNSC, BRIP1 in LUSC and ATM in STAD." (PMID 26689913, 2015). "Amplifications of 8 FA genes are identified across 22 carcinomas; 2 of the carcinomas contain amplification in two FA genes (FANCG with FANCI and BRIP1 with RAD51C)." (PMID 26438152, 2015). "We highlight an underexplored role of homologous recombination deficiency in non-traditional cancer types and postulate a tumor-agnostic approach to the use of PARP-inhibitors in BRIP1-mutated tumors." (PMID 40988318, 2025).
cancer (continued). "While, e.g., DCAF7 and CDH2 displayed continuous changes across lineage types occurring during cancer progression, others such as TCIM or BRIP1 were expressed transiently at higher levels in asymmetric or only in symmetric (i.e., only invasive tumor cell) lineages, respectively." (PMID 38553478, 2024). "The genetic alteration, CNV, and SNV of BRIP1 were observed in various cancers, and CNV could regulate BRIP1 expression in several cancer types." (PMID 36907870, 2023). "In addition to BRCA1 and BRCA2, many other HRR mediators (ATM, BRIP1, CHEK2, NBS1 or RAD51C) are frequently defective in cancer." (PMID 37298484, 2023). "Of interest, positive correlations between TMB/neoantigen and BRIP1 expression were observed in LUAD, PRAD, and STAD, suggesting BRIP1 could be an immunotherapy target in these cancers." (PMID 36907870, 2023). "The upregulation of BRIP1 was found in 17 cancers, and no statistical differences exist in 4 cancers." (PMID 36907870, 2023). "Of these, seven genes (BRIP1, ERCC4, FANCD2, FANCG, FANCI, MAD2L2, PPP2R2A) were previously related to the platinum sensitivity/resistance of different types of cancer cells, with NPEPPS being reported for the first time as a platinum drug sensitivity regulator." (PMID 35209078, 2022). "Heterozygous mutations of BRCA2, BRIP1 (FANCJ) and PALB2 (FANCN) are not sufficient to develop FA phenotypes, but they are associated with a dramatic increased risk for breast, ovarian and other cancers." (PMID 31535215, 2019). "In particular, increased BRIP1 transcript levels were found in tumors with an estrogen receptor-negative, progesterone receptor-negative or HER-2-positive status, in basal-like cancers and in stage 2 tumors as compared to stage 1 carcinomas." (PMID 28317894, 2017). "Besides, the opposite correlation between BRIP1 expression and MSI and TMB among various cancers may also result in different clinical outcomes." (PMID 36907870, 2023). "Interestingly, no significantly decreased expression of BRIP1 was observed among all the cancer types in this study." (PMID 36932143, 2023). "Pan-cancer studies have recently emerged as a novel perspective for understanding the molecular mechanisms of the occurrence and the development of human cancers, and we failed to obtain the pan-cancer analysis of BRIP1 across human tumors from the literature search." (PMID 36907870, 2023). "Besides, the BRIP1 expression related OS also lacked 12 cancer types." (PMID 36932143, 2023). "However, there is a lack of a comprehensive pan-cancer analysis of BRIP1." (PMID 37153833, 2023). "For comparison, no BRIP1, 2 RAD51C, and 2 RAD51D large mutations per ~ 11,000 subjects are reported in the gnomAD database, and 2 BRIP1, 5 RAD51C, and 3 RAD51D large mutations per ~ 10,000 cancer-free women older than age 70 are documented in the FLOSSIES database." (PMID 32359370, 2020).
tumor (116 papers, 2007 to 2026). "BRIP1 expression was subsequently examined in tumor tissues from 60 CRC patients, and its associations with clinicopathological characteristics and clinical outcomes were assessed." (PMID 41597333, 2025). "We identified two patients with BRIP1 heterozygous variants, with one of these patients exhibiting loss of heterozygosity in their tumor samples." (PMID 40766138, 2025). "It is unclear why two of the four patients with a germline BRIP1 pathogenic variant had a GIS-negative tumour." (PMID 36765687, 2023). "We further carried out immune infiltration analysis, and the relationships between BRIP1 and immune-related genes and tumor mutation burden (TMB)-microsatellite instability (MSI) as well as immunotherapy and targeted drug responses were subsequently analyzed." (PMID 37153833, 2023). "Of these, 11 (19%) patients had BRCA1/2-mutated tumors (7 BRCA1 and 4 BRCA2), 2 (4%) patients had tumors with BRIP1 mutations, and 1 (2%) patient had a tumor with a two-copy deletion of RAD51C." (PMID 34552099, 2021). "BRIP1 is a member of the RecQ DEAH helicase family, and is encoded by BRIP1, a tumor suppressor gene involved in the DNA repair pathway, via its interaction with BRCA1." (PMID 32300589, 2020). "Additional germline testing for BRIP1 gene mutation was proposed based on high allele frequency of BRIP1 mutation in tumor tissue." (PMID 31064327, 2019). "Further germline testing for BRIP1 gene mutation was done based on high allele frequency of BRIP1 mutation in tumor tissue." (PMID 31064327, 2019). "The BRIP1 mutation was clearly a germline mutation as demonstrated by its presence in all tumor samples analyzed and its presence in DNA extracted from peripheral blood and buccal swabs." (PMID 29755699, 2018). "Nonetheless, the directionality of survival trends was consistent with TCGA findings, supporting the hypothesis that reduced BRIP1 expression may be associated with more aggressive tumor behavior." (PMID 41597333, 2025). "Two of the four BRIP1 pathogenic variants were detected in women with a GIS-positive tumour." (PMID 36765687, 2023). "In all tumor samples, the total mutation frequency of BRIP1 was 2.18% (242/11,066)." (PMID 36932143, 2023). "The specific HRR mutations identified in the 21 tumour samples were: BRIP1 (n = 5), CDK12 (n = 3), RAD54L (n = 2), RAD51B (n = 2), RAD54L rearr (n = 1), ATM rearr (n = 1), FANCA rearr (n = 1), FANCD2 (n = 1), FANCL rearr (n = 1), FANCL (n = 1), RAD51C (n = 1), RAD52 del (n = 1), XRCC3 rearr (n = 1)." (PMID 30353044, 2018). "Among these genes, BRIP1 showed significant differential expression between tumor and normal tissues, as well as normal gastric mucosal epithelial cells and GC cells." (PMID 41828629, 2026). "When normalized as the tumor-to-non-tumor expression ratio, the mean BRIP1 expression level was 2.71 ± 1.62." (PMID 41597333, 2025). "miR-664b-3p was found to enhance apoptosis (programmed cell death) by regulating the levels of BRIP1, which is a protein that interacts with BRCA1 (a tumor suppressor gene commonly associated with BC)." (PMID 38832155, 2024). "The poorly differentiated invasive ductal breast carcinoma is a triploid tumour with copy gains in BRIP1 and ATR and a high number of alternations." (PMID 39702187, 2024). "The results of this analysis provided important new insights into the dysregulation of BRIP1 in tumor biology and identified potential therapeutic targets and prognostic indicators for tumors." (PMID 36932143, 2023). "In a study of patients with tumor CGP-identified mutations in moderate risk breast and ovarian CSGs (ATM, BRIP1, CHEK2, PALB2, RAD51C, and RAD51D), 24% of patients with germline variants would not have met criteria for germline testing." (PMID 37568048, 2023).